RNU2-15P (RNA, U2 small nuclear 15, pseudogene)
Gene: Small nuclear RNA gene on chromosome 1 (65,415,816 to 65,416,006, forward strand). Ensembl gene ENSG00000222624.
Homologues: Orthologues: chimpanzee U2 (99% identical), macaque U2 (93% identical). Paralogues in human: RNU2-8P (80% identical), RNU2-48P (79% identical), RNU2-14P (78% identical), U2 (78% identical), RNU2-64P (77% identical), U2 (77% identical), RNU2-33P (77% identical), RNU2-3P (77% identical), RNU2-61P (76% identical), RNU2-23P (76% identical), RNU2-43P (75% identical), RNU2-4P (75% identical), and 65 more.